ID2 (inhibitor of DNA binding 2)
Diseases named in the same sentence as ID2 in open-access papers (continued):
Sharing a sentence is not in itself a finding about the gene and the disease.
neuroblastoma (28 papers, 2007 to 2025). Neuroblastoma (NB) is the most common solid, extracranial childhood tumor. "Here we show that two miRNAs upregulated on differentiation of neuroblastoma cells – miR-9 and miR-103 – restrain ID2 expression by directly targeting the coding sequence and 3′ untranslated region of the ID2 encoding messenger RNA, respectively." (PMID 22848373, 2012). "This suggested that miR-9 and miR-103 up-regulation in differentiating neuroblastoma cells might be implicated in the ID2 decrease." (PMID 22848373, 2012). "Moreover, an ID2 mRNA mutated in miR-9 and miR-103 target sites was able to rescue the decrease in proliferation rate and N-Myc expression occurring when neuroblastoma cells are induced to differentiate by retinoic acid." (PMID 22848373, 2012). "It has been reported that ID2 overexpression induced neuroblastoma dedifferentiation and enhanced chondrogenic proliferation." (PMID 39904483, 2025). "These included SKP2 or MYCN, confirming prior data, and ID2, which drives oncogenesis in other RB1null and RB1wt/MYCNamp contexts, including neuroblastoma." (PMID 32572160, 2020). "We recently reported that Id2 knockdown of mouse neuroblastoma (Id2kd-N2a) cells are rejected by most mice following inoculation and that the same mice then fail to grow tumors when subsequently rechallenged with wild-type Neuro2a cells." (PMID 29377881, 2018). "A mouse model of neuroblastoma was investigated using an Id2 knockdown whole cell vaccine in combination with checkpoint inhibition." (PMID 29377881, 2018). "In neuroblastoma the Id2 gene is activated by Myc oncoproteins, which leads to the inhibition of the pRb tumor suppressor pathway with consequent cell-cycle progression." (PMID 28122577, 2017). "A modified HEB HLH domain has been shown to interfere with and inhibit Id2 in human neuroblastoma cells." (PMID 28122577, 2017). "Retinoic acid-induced up-regulation of two miRNAs (miR-9 and miR-103) during neuroblastoma cell differentiation inhibits Id2 expression and cell growth." (PMID 28122577, 2017). "To understand the role of Id2 in neuroblastoma cell plasticity, we targeted Id2 expression in Neuro2a cells with lentiviral vectors expressing Id2shRNA and found that Id2 is the key molecule modulating phenotypic transition in neuroblastoma." (PMID 26079374, 2015). "A critical characteristic of RAP in mouse neuroblastoma is the necessary and abundant expression of inhibitor of differentiation protein 2 (Id2) in its anchorage dependent phenotype." (PMID 26079374, 2015). "To this end, we tested the use of Id2-kd N2a cells in a therapeutic treatment model of established neuroblastoma tumor." (PMID 26079374, 2015). "Therapeutic vaccination with Id2-kd N2a cells alone suppressed tumor growth even in established neuroblastoma tumors and when used in combination with immune checkpoint blockade eradicated large established tumors." (PMID 26079374, 2015). "It has been proved that inhibition of Id2 function is possible in vitro, and it results in reduction of tumorigenic properties in neuroblastoma cells and promotion of cells differentiation." (PMID 25771836, 2015). "We targeted Id2 in the mouse neuroblastoma cell line, as this was the most dominant and differentially expressed protein (~20 fold) between the anchorage dependent and independent cell phenotypes." (PMID 26079374, 2015). "Knock down of Inhibitor of differentiation protein 2 (Id2-kd) in mouse neuroblastoma whole tumor cells rendered these cells immunogenic." (PMID 26079374, 2015). "The role of Id2 protein in physiological cell cycle progression and in neuroblastoma (NBL) pathogenesis was proposed by Lasorella." (PMID 25771836, 2015). "MiR-9 increases retinoic acid induced neuronal differentiation in neuroblastoma cells by inhibiting the neuronal differentiation repressor ID2." (PMID 24714615, 2014).
neuroblastoma (continued). "Taken together, the results show that Id2 functions as a negative regulator of TGFβ/Smad in neuroblastoma cells and activation of the TGFβ pathway is at least partially responsible for the transition of AD cells to an AI phenotype." (PMID 24376712, 2013). "BrdU incorporation revealed a significant decrease in cell proliferation and cell cycle analysis exhibited fewer cells in the S-phase of the cell cycle of Id2-suppressed neuroblastoma cells compared to cells transfected with a control siRNA." (PMID 24376712, 2013). "In conclusion, Id2 and TGFβ are key regulators of phenotypic transition in neuroblastoma tumor cells." (PMID 24376712, 2013). "Taken together, these results suggest that Id2 most likely plays a significant role in neuroblastoma tumor cell growth." (PMID 24376712, 2013). "Overexpression of miR-9 and miR-103 in neuroblastoma cells reduces proliferation and promotes differentiation, as it was shown to occur upon ID2 inhibition." (PMID 22848373, 2012). "We performed a bioinformatic analysis to identify microRNAs recognizing ID2 mRNA (accession number NM_002166.4), focusing on the set upregulated upon retinoic acid treatment of the neuroblastoma cell line SK-N-BE." (PMID 22848373, 2012). "We have identified two microRNAs – miR-9 and miR-103 – that are upregulated by RA in neuroblastoma cells, directly inhibit ID2 expression, impair proliferation and trigger differentiation." (PMID 22848373, 2012). "On the contrary, ID2 is down regulated by retinoic acid in neuroblastoma cell lines such as SH-SY5Y and others." (PMID 22848373, 2012). "ID2 protein expression, intracellular localisation and stability are downregulated when neuroblastoma cell lines are induced to differentiate." (PMID 22848373, 2012). "We identify miR-9 and miR-103 – upregulated by retinoic acid treatment – as negative regulators of ID2 and differentiation promoting microRNAs in neuroblastoma cells." (PMID 22848373, 2012). "Specifically, ID2 plays a key role in proliferation of glioma stem-like cells, it supports tumour cell migration, and it is frequently upregulated in neuroblastoma, a childhood tumour arising from aberrant development of neural crest cells." (PMID 22848373, 2012). "On the basis of our findings, we propose that miR-9 and miR-103 – acting on ID2 mRNA – directly affect production of the ID2 protein in neuroblastoma cells." (PMID 22848373, 2012). "Nevertheless, the overexpression of Id genes in cancer is frequently governed by bona fide oncogenes, such as MYC driven Id2 expression in neuroblastoma cells and beta-catenin driven Id2 expresion in colon cancer cells." (PMID 21293053, 2010). "The prognostic value of high ID2 expression has already been demonstrated in other cancer types such as neuroblastoma and prostate cancer." (PMID 19129913, 2009). "We observed that N1E-115 cells express both HIF1α and HIF2α, their common target genes VEGF and adrenomedullin as well as several neuroblastoma classical markers including neuropilin-1, neuronal-specific enolase, Id2 and chromogranin A." (PMID 17655754, 2007). "To confirm this observation, we studied the expression of Id2 and CgA markers, which are respectively induced and downregulated during hypoxia-mediated neuroblastoma dedifferentiation." (PMID 17655754, 2007). "With the exception of ID2, all the other immune genes (CD8a, IL2, IL7R, IL6, ID3, and CXCR3) were also highly expressed in low-risk neuroblastoma patients further confirming the significance of these immune genes in neuroblastoma cases with favorable outcomes." (PMID 36068918, 2023). "ID1 and ID2, both characterized by 1 bp insertions and deletions at long thymine homopolymers attributed to replication slippage and found in most cancer entities, were also recurrently identified in neuroblastoma genomes." (PMID 37868040, 2023). "Moreover, the ID2 gene, a key regulator in the phenotypic transition of neuroblastoma tumor cells, is also present." (PMID 30791380, 2019).
neuroblastoma (continued). "In neuroblastoma, an extracranial cancer mostly occurring in infants and children and characterized by the amplification and overexpression of the oncogene N-Myc (neuronal Myc), Id2 is transcriptionally activated by Myc oncoproteins." (PMID 28122577, 2017). "To verify this statement, we knocked down Id-1 or Id-2 with shRNA in neuroblastoma cells." (PMID 29079782, 2017). "Id2-knockdown neuroblastoma cells (Id2kd-Neuro2a) have shown to be immunogenic." (PMID 28122577, 2017). "Although irradiation of tumor cell vaccines is known to evoke potent anti-tumor immunity in melanoma and lung cancer models, we find neither a favorable nor particularly adverse effect of irradiation on the antigenic properties of the Id2-kd cells in neuroblastoma." (PMID 26079374, 2015). "In both mouse and human neuroblastoma tumor cells, Id2 maintains the proliferative phenotype and any alteration in its expression perhaps due to microenvironmental signals may account for its phenotypic switching to a more dormant anoikis resistant phenotype." (PMID 24376712, 2013). "Id2 is known to be a key negative regulator of TGFβ-induced EMT in epithelial cells suggesting that the effect of Id2 on the neuroblastoma phenotypic switch may be mediated by TGFβ." (PMID 24376712, 2013). "Either transient or stable knock-down of Id2 in AD cells and forced overexpression in AI cells resulted in the cells adapting characteristics of the other phenotype and confirmed the key role of Id2 in reversible adaptive plasticity of neuroblastoma cells." (PMID 24376712, 2013). "In addition, we found that Id2 inhibition induced significant apoptosis in the AD phenotype of all the neuroblastoma cells studied." (PMID 24376712, 2013). "Similarly, differential expression of Id2 and other genes of interest were also observed in the AD and AI phenotypes of human neuroblastoma cell lines, SK-N-SH and IMR-32; as well as in primary human tumor specimens." (PMID 24376712, 2013). "Due to its known function as an effector of n-myc and its remarkable differential expression in the cell phenotypes, we reasoned that Id2 could play a key role in reversible adaptive plasticity in the neuroblastoma cells." (PMID 24376712, 2013). "Furthermore, immunofluorescence staining revealed the expression of Id2 protein in human and mouse neuroblastoma tumor specimens." (PMID 24376712, 2013). "To clarify this aspect, we asked whether ectopic expression of miR-9 and miR-103 affected neuroblastoma cell proliferation, differentiation marker expression, and neurite formation as it was shown to occur on ID2 inhibition by the 13I protein." (PMID 22848373, 2012). "Indeed, downregulation of ENH expression prevents relocalization of ID2 into the cytoplasm in differentiated neuroblastoma cells." (PMID 19129913, 2009). "Therefore, FHL2 is proposed to be a repressor of the oncogenic activity of Id2 in neuroblastoma." (PMID 28122577, 2017). "However, this checkpoint may be override by up-regulated Id2 leading to hyper-proliferation and development of neuroblastoma." (PMID 28122577, 2017). "Id2 was also found to be expressed in the AD phenotype of human cell lines as well as in primary human tumor specimens and many of the other survival/proliferation genes of interest were also differentially expressed in human neuroblastoma AD and AI cell phenotypes." (PMID 24376712, 2013). "Consequently, if ID2 inhibition is significant for their function, overexpression of the two microRNAs should mimic, at least partly, the effects observed upon 13I expression in neuroblastoma cells." (PMID 22848373, 2012). "Hence, our findings strongly support the hypothesis that the microRNA-mediated ID2 inhibition has a role in controlling neuroblastoma cell differentiation." (PMID 22848373, 2012). "ID1 and ID2 correlated positively with SNV signature SBS18, which indicates co-occurrence of DNA damage by ROS and replication slippage in MYCN-amplified neuroblastomas." (PMID 37868040, 2023).
neuroblastoma (continued). "Further support for our model comes from genome-wide analyses showing that CDKN1C and ID2 are likely to be direct targets of ASCL1 in GBM and neuroblastoma cells." (PMID 35149717, 2022). "However, whether a correlation exists between N-Myc and Id2 gene/protein expression in neuroblastoma, or if the Myc action in vivo is mediated by Id2 in other cancer types like epidermal neoplasia and lymphomagenesis are still controversial and would need further investigation." (PMID 28122577, 2017). "Down-regulation of MYCN, ID2, TERT and FN1 has been also reported in neuroblastoma cells undergoing differentiation upon exposure to retinoids." (PMID 26893368, 2016). "Concomitantly, genes that critically support neuroblastoma proliferation were down-regulated, such as MYCN, inhibitor of differentiation 2 (ID2) and MYB." (PMID 27242543, 2016). "Id2 is critical for cell proliferation and is the oncogenic effector of N-MYC in human neuroblastoma." (PMID 24376712, 2013). "Previous reports demonstrated that Id2 is a direct transcriptional target of HIF-1α in neuroblastoma cells, suggesting that HIF-1α and ID2 may function in a feed-forward loop in HSCs." (PMID 35775482, 2022). "ID2 is a helix-loop-helix transcription factor controlled by MYC proteins that blocks differentiation and promotes cell proliferation, and MYB is a transcription factor that cooperates with MYCN in cell cycle regulation of MYCN-amplified neuroblastomas." (PMID 27242543, 2016). "Id2-kd neuroblastoma (Neuro2a) cells (Id2-kd N2a) failed to grow in most immune competent mice and these mice subsequently developed immunity against further wild-type Neuro2a tumor cell challenge." (PMID 26079374, 2015). "Indeed, down-regulation of Id2 expression in the AD phenotype of neuroblastoma cells not only decreased proliferation and induced apoptosis but also resulted in over-activation of anoikis resistant pathways." (PMID 24376712, 2013). "The role of ID2 has been studied in several types of cancer (i.e., prostate, breast, colorectal, neuroblastoma, and very recently small cell lung cancer), but to date, nothing is known about the expression of ID2 in non-small cell lung cancer, which affects 80% of patients with lung malignancies." (PMID 19129913, 2009). "However, a direct binding of MYCN to Id2 promoter has not been demonstrated and Id2 expression does not seem to be associated with MYCN amplification or expression in human neuroblastoma." (PMID 18493594, 2008).
glioblastoma (20 papers, 2012 to 2024). The most malignant astrocytic tumor (WHO grade IV). "In glioblastoma, the oncoprotein N-Myc increases ID2 expression and binds with Rb, resulting in its deactivation and subsequently promoting cell cycle progression." (PMID 38254880, 2024). "ID2 and ETS2 genes were found to be expressed by the tumour-associated microglia isolated from human glioblastoma tumour biopsies." (PMID 39019900, 2024). "More recently, ID2 levels have been shown to influence neuronal differentiation of human glioblastoma stem cells, with elevated ID2 reducing the number of βIII-tubulin positive cells." (PMID 35573698, 2022). "ASCL1 phosphorylation and ID2 upregulation are roadblocks to glioblastoma stem cell differentiation." (PMID 36147490, 2022). "ID2 plays a critical role in the survival of aggressive cancer cells and positively modulates the activity of HIF2α in glioblastoma." (PMID 34975891, 2021). "For ID2 it has been shown that expression is required to maintain glioma, glioblastoma, head and neck, and colorectal cancer stem/stem-like cells." (PMID 30642388, 2019). "Id2 and Id4 play a crucial role in regulating the glioblastoma multiforme (GBM) stem-like cells differentiation, thus reducing their cancer initiating potential." (PMID 28122577, 2017). "We found that inhibitor of DNA binding 2 (ID2) expression levels significantly correlate with the ability of glioblastoma (GBM)-derived cell lines to survive glucose deprivation." (PMID 28206987, 2017). "A recent study reported that decreased ID2 expression enhanced chemosensitivity to semustine, teniposide, and temozolomide in the U87 cell line by promoting apoptosis of glioblastoma cells." (PMID 29190891, 2017). "It is noteworthy that in a recent study of human glioblastoma cells/tissue, an important role was established for ID2 in modulating the cellular effects of hypoxia and its activation of the HIF2α pathway." (PMID 27144179, 2016). "miR-9 restrains the tumorigenic potential and is associated to a better prognosis of glioblastoma, it suppresses mesenchymal differentiation of glioblastoma cells and inhibits glioblastoma cancer stem-like cell proliferation, which is instead promoted by ID2." (PMID 22848373, 2012). "ID2 decreases intracellular reactive oxygen species (ROS) production through the inhibition of oxidative phosphorylation in the mitochondria, thus promoting tumor cell survival in glioblastoma." (PMID 38254880, 2024). "It has been demonstrated that in glioblastoma, ID2 can bind to RB1 and thus inhibit its function." (PMID 38254880, 2024). "ID2 has previously been identified as a key mediator of glioblastoma cell “stemness”." (PMID 32142668, 2020). "Moreover, the phosphatase PP2A has been shown to maintain high Id2 levels in glioblastoma: in contrast, inhibition of selected PP2A subunits in glioblastoma-derived stem cells (GSCs) decreases Id2 levels as the result of regained protein phosphorylation and enhanced degradation." (PMID 28122577, 2017). "According to studies, CBD downregulate the metastatic factor (ID1) and up-regulates the pro-differentiation factor (ID2), which results in a significant reduction in the invasion glioblastoma (GBM), inhibition of GBM dispersal ex vivo, and reduction in tumor growth and Id-1 expression in vivo." (PMID 36568260, 2022). "Since ID2 can prevent proteasomal degradation of HIF-2α in glioblastoma cells by binding to VHL protein present in the Cullin ring E3 ubiquitin ligase (CRL) complex, we examined whether ID2 could inhibit HIF-1α degradation in HSCs." (PMID 35775482, 2022). "A targeted network analysis of gene expression profiles in colorectal cancer cells revealed that ONC201 downregulates stem cell pathways such as Wnt signaling and modulates genes (ID1, ID2, ID3 and ALDH7A1) known to regulate self-renewal in colorectal, prostate cancer and glioblastoma." (PMID 28767654, 2017).